FBXW7 (F-box and WD repeat domain containing 7)
Diseases named in the same sentence as FBXW7 in open-access papers (continued):
Sharing a sentence is not in itself a finding about the gene and the disease.
tumor (continued). "Therefore, loss of FBXW7 promotes tumor growth and blocks differentiation, effects that are in part driven by aberrant activation of Wnt signaling." (PMID 41373479, 2025). "In conclusion, mutations of histone methylation gene KMT2D may modulate tumor-induced Treg cell trafficking via the FBXW7-NOTCH-MYC/TGF-β1 axis." (PMID 39113693, 2024). "Together, KMT2D mutations promoted tumor progression by regulating FBXW7-NOTCH-MYC axis in DLBCL." (PMID 39113693, 2024). "Furthermore, in murine tumor models undergoing radiotherapy, mTOR inhibitors delay tumor progression associated with FBXW7 mutations or deletions." (PMID 39749199, 2024). "Fat metabolism, regulated by FBXW7, is also linked to tumor growth in CRC." (PMID 39749199, 2024). "At the same time, the authors demonstrated that the identified variant resulted in downregulation of FBXW7 and loss of function, which provided empirical evidence that patients with DEDHIL may have increased tumor susceptibility." (PMID 39364007, 2024). "Furthermore, we discuss the consequences of FBXW7 loss or dysfunction in tumor progression and underscore its potential as a prognostic and therapeutic biomarker." (PMID 39749199, 2024). "circFBXW7 is an antioncogenic product encoded by the Fbxw7 protein that acts as a tumor suppressor." (PMID 39727990, 2024). "Therefore, aberrant FBXW7 expression is strongly associated with carcinogenesis, tumor progression, metastasis, poor outcomes in cancer patients, and resistance to treatment." (PMID 38027013, 2023). "In contrast, hsa-miR-769-5p related to FBXW7 mutation may be involved in grade 1 tumors and is less likely to be involved in tumor aggressiveness." (PMID 37047300, 2023). "For example, overexpression of mitochondrial antiviral-signalling protein(Mavs) makes the FBXW7 deficient tumor sensitive to PD-1 blocking, delays the growth of Fbxw7-deficient tumors and prolongs the survival of anti-PD-1-treated Fbxw7-deficient tumor-carrying mice." (PMID 36998461, 2023). "FBXW7 is a critical tumour suppressor that is frequently mutated in human cancers." (PMID 37686662, 2023). "Among the most commonly mutated of these, particularly in non‐endometrioid tumours, is FBXW7—the substrate recognition component of an SCF complex responsible for the ubiquitylation and degradation of multiple oncogenic substrates, including cyclin E, mTOR and Jun." (PMID 37589076, 2023). "Many cancers have frequent FBXW7 mutations, and FBXW7 functions as a tumor suppressor." (PMID 37202390, 2023). "Accordingly, loss of FBXW7 increases tumor incidence in mice." (PMID 38155930, 2023). "FBXW7 as a tumour suppressor is mutated or inhibited in human cancers with high frequency." (PMID 36881608, 2023). "Yang et.al report circ-FBXW7 and a functional protein encoded by the circRNA, which could inhibit proliferation and cell cycle acceleration in tumour." (PMID 36861189, 2023). "Notably, FBXW7 is commonly rendered inactive by mutations, deletions, or promoter hypermethylation in some neoplasms, including hematologic malignancies, breast, colon, uterine, and lung cancer." (PMID 38027013, 2023). "In summary, we identified different miRNA signatures involved in FBXW7 mutations or high mitotic indices in rectal NETs, which may play a critical role in tumor behavior." (PMID 37047300, 2023). "FBXW7 is a tumor suppressor that is frequently mutated in many cancer types." (PMID 36530167, 2023). "FBXW7 encodes an E3 ubiquitin ligase complex member and tumor suppressor." (PMID 37902422, 2023). "Future studies aimed to reactivate FBXW7 functions may take advantage of the fact that for the most part tumor cells are heterozygous and harbor both wild type and mutated copies." (PMID 35346215, 2022). "Furthermore, some studies confirmed that FBXW7 downregulation in tumor tissues is associated with poor outcomes and progression of HCC." (PMID 36159747, 2022).
tumor (continued). "In summary, circPSD3 inhibits tumor metastasis by repressing the miR-25-3p/FBXW7-EMT axis and might be developed as a potential diagnostic and therapeutic target for ccRCC." (PMID 35295711, 2022). "Mutations in tumor suppressors FBXW7 and ATM display a higher prevalence in BRAF mutated cancers." (PMID 36079062, 2022). "All these data suggest that FBXW7 is a functional target of miR-103a-3p, and FBXW7 down-expression in CC tumor tissues may be caused by upregulation of miR-103a-3p." (PMID 35094292, 2022). "FBXW7 participates in the polarization of tumor-associated macrophages via different pathways." (PMID 35814468, 2022). "Our analysis also yielded RBM10 and FBXW7 as frequently mutated genes in metastatic ccRCC tumours." (PMID 35231161, 2022). "Reportedly, FBXW7 is often implicated in the progression of diverse cancers as a tumor suppressor." (PMID 35965327, 2022). "Since the stem cell-like characteristics are closely associated with tumor recurrence and chemotherapy resistance, we speculated that the expression of FBXW7 may affect the drug sensitivity of HCC cells." (PMID 36159747, 2022). "FBXW7 is encoded at 4q31.3 and was identified as a positively selected tumour suppressor." (PMID 33741915, 2021). "Moreover, a low protein expression of FBXW7 is associated with poor pathological features, including a large tumor size, high pathological grading, and advanced TNM staging." (PMID 34659544, 2021). "FBXW7 is a E3-ubiquitin ligase playing tumor suppressive roles by targeting some oncoproteins for ubiquitylation and proteasome degradation, so our results demonstrated another fate of tumor suppressor genes with nonsense mutations in tumor tissue." (PMID 34922552, 2021). "However, in this case, the role that FBXW7 plays in tumorigenesis would be more a consequence than a cause of tumor transformation." (PMID 32316282, 2020). "Remarkably these lines were resistant to the effects of IRF1 expression, suggesting loss of Fbxw7 function may render cancers resistant to some of the tumour suppressor activities of IRF1." (PMID 30854564, 2019). "Furthermore, lower FBXW7 expression is associated with poor clinical pathology features, including large tumor size, high pathological grading, and advanced TNM stage." (PMID 30086763, 2018). "To clarify the initiating role in gastric carcinogenesis as well as the histologic characterization of tumor in Fbxw7 allele haploinsufficient mice, we generated Fbxw7 heterozygous knockout mice (Fbxw7+/−) and treated them with chemical carcinogen N-methyl-N-nitrosourea (MNU) at 5–6 weeks of age." (PMID 28422719, 2017). "We have identified a potential novel drug candidate for FBXW7-deficient tumours." (PMID 28829765, 2017). "Our previous studies showed that temporal pharmacological inhibition of the mTOR pathway was sufficient to suppress the tumor development contributed by Fbxw7 loss, suggesting that the Fbxw7-mTOR pathway plays a major role in this radiation-induced carcinogenesis mouse model." (PMID 27376155, 2016). "Considering the multiple challenges to treatment response posed by a mutated tumour suppressor gene, elucidating FBXW7's mechanisms of action could be a breakthrough for cancer therapy." (PMID 25860929, 2015). "Our previous studies using mouse models showed that temporal pharmacological inhibition of the mTOR pathway was sufficient to suppress the tumor development contributed by Fbxw7 loss, suggesting that the Fbxw7-mTOR pathway plays a major role in this radiation-induced carcinogenesis mouse model." (PMID 26575021, 2015). "Deletion or mutation of the FBXW7 gene may result in impaired degradation of multiple targets and their consequent accumulation, which may cooperatively contribute to tumor development." (PMID 26575021, 2015).
tumor (continued). "Our results in this study showed that temporal pharmacological inhibition of mTOR pathway after radiation was sufficient to suppress the tumor development contributed by Fbxw7 loss, suggesting that Fbxw7-mTOR pathway plays a major role in this radiation-induced carcinogenesis mouse model." (PMID 23454868, 2013). "Next, we investigated whether temporal mTOR inhibition by rapamycin can prevent mice from Fbxw7 loss-induced tumor development." (PMID 23454868, 2013). "Mutation/loss of the Fbxw7 gene may cause impaired degradation of multiple targets, and as a result constitutive accumulation of these targets may cooperatively contribute to tumor development." (PMID 23454868, 2013). "In this study, we investigated whether inhibition of mTOR signaling pathway by rapamycin was able to prevent the tumor development resulted from loss of Fbxw7 in mice." (PMID 23454868, 2013). "In the light of these results on mouse models of cancer, it is possible that specific genetic variants in human FBXW7, or indeed of other common human tumor suppressors, may also affect the patterns of allelic losses in tumors." (PMID 22348067, 2012). "Indeed, FBXW7 itself behaves as a haploinsufficient tumor suppressor gene: the loss of one functional allele is enough to promote epithelial tumor growth in a mouse model." (PMID 17326833, 2007). "Moreover, Fbxw7-mutant tumors responded well to immune checkpoint inhibitors, indicating that Fbxw7 deficiency is likely to induce a severe immune response responsible for accelerating tumor formation and growth." (PMID 38212325, 2024). "Moreover, the loss of FBXW7 has been extensively studied and consistently linked to the pathogenesis of cancer, as well as tumor metastasis, poor clinical outcomes, and resistance to a range of cancer treatments including chemotherapy, radiation therapy, and immunotherapy." (PMID 37752997, 2023). "Interestingly, this ubiquitination-mediated control of IFNγ signaling at the level of IFNγ-R1 may constitute a more common mechanism, since recently another ubiquitin ligase, FBXW7, was implicated in governing IFNγ-R1 signaling in breast cancer." (PMID 35395848, 2022). "Several studies have shown that the loss-of-function mutation of FBXW7 is most often found in human cancers among the ~ 70 F-box genes identified in the human genome, meaning that approximately 6% of all cancers contain FBXW7 mutations and supporting the role of FBXW7 as a tumor suppressor." (PMID 33676554, 2021). "This suggests that FBXW7 deficiency in bone marrow cells, including macrophages, MDSCs, and dendritic cells, may be involved in different stages of cancer development and might regulate tumor growth and metastasis through different mechanisms." (PMID 33260160, 2020). "In addition, FBXW7 is a tumor suppresser that is frequently mutated in certain types of human cancer, but the exact mechanisms underlying its tumor suppressive function remain unclear." (PMID 28423622, 2017). "Thus we assume that inhibition of mTOR activity by rapamycin may act a major brake on tumor development in Fbxw7 deficient mice." (PMID 23454868, 2013). "FBXW7 functions as a tumor suppressor by targeting oncogenic substrates, such as c‐Myc and Notch, for degradation." (PMID 41522471, 2026).
tumor (continued). "FBXW7 (F-box and WD repeat domain containing 7) is a tumor suppressor and component of an E3 ubiquitin ligase complex, which is responsible for tagging proteins for proteasomal degradation." (PMID 41869454, 2026). "FBXW7 (F-box and WD repeat domain-containing 7) is a classic tumor suppressor that promotes ubiquitylation and degradation of various oncoproteins." (PMID 41799933, 2026). "miR-192-5p facilitates proliferation by repressing the proapoptotic factor BIM; miR-223-3p enhances tumor growth by directly targeting FBXW7, a tumor suppressor that controls the stability of key cell cycle regulators such as c-MYC and c-Jun." (PMID 41596525, 2026). "FBXW7, a well-characterized tumor suppressor, mainly functions by promoting the degradation of oncogenic regulators involved in cell cycle progression and cellular differentiation, such as cyclin E1, c-Myc, c-Jun and Notch." (PMID 40721413, 2025). "The tumor suppressor FBXW7, which is frequently downregulated in adenocarcinomas, is not expressed in SCCPs, and this phenotype leads to the accumulation of oncoproteins (e.g., c-MYC) that drive invasiveness." (PMID 40746833, 2025). "FBXW7, as a critical tumor suppressor, targets various substrates for proteasome-mediated degradation of oncoproteins, including cyclin E, c-Myc, Mcl-1, mTOR, Jun, and Notch." (PMID 39747664, 2025). "KLHL37 directly interacted with N-Myc to disrupt N-Myc–FBXW7 interaction, thereby stabilizing N-Myc and enabling tumor progression." (PMID 40493396, 2025). "Fbxw7 is also recognized as a tumor suppressor due to its ability to target oncogenic proteins like c-Myc, Notch, MCL1, and c-Jun." (PMID 40901482, 2025). "By controlling C/EBPδ stability, FBXW7 acts as a critical regulator of macrophage-mediated immunity, highlighting its dual role in both tumor suppression and immune modulation." (PMID 40534867, 2025). "In our study, we observed SUMF2 interaction with the tumor suppressor FBXW7 using a BioGRID dataset and Pathway Commons analysis." (PMID 39915362, 2025). "In RCC, FBXW7 overexpression induces cell apoptosis and inhibits tumor proliferation and metastasis." (PMID 40083925, 2025). "Upon mitotic arrest caused by anti-microtubule drugs, FBXO45-MYCBP2 functions in mitotic cell fate decision by ubiquitinating the tumor suppressor FBXW7, which leads to FBXW7 degradation and mitotic slippage." (PMID 41052634, 2025). "By mediating c-MYC degradation, FBXW7 disrupts the signaling pathways that drive M2 polarization, thereby suppressing the tumor-promoting functions of these macrophages." (PMID 40534867, 2025). "FBXW7 suppresses CRC progression by inhibiting tumor cell migration and metastasis, leading to improved overall survival and disease-free survival." (PMID 41373479, 2025). "In our study, the CTNNB1, FBXW7, NOTCH2 mRNA as well as the ARID1A promoter hypermethylation biomarkers were associated with the HGSOC tumor stage, suggesting possible implications for the prognosis, despite our study lacking more in-depth prognosis data." (PMID 40002854, 2025). "Circ-FBXW7, for example, has been demonstrated to interact with and stabilize the tumor suppressor FBXW7." (PMID 40896358, 2025). "Within the macrophage and tumor immune microenvironment, Fbxw7 was observed to suppress M2-like polarization of tumor-associated macrophages, thereby limiting tumor progression." (PMID 40034124, 2025). "FBXW7 has been shown to degrade many key regulators of cellular function by targeting them at cell cycle checkpoints, tumor cell proliferation, DNA damage repair, genomic instability, regulation of cell survival, and tumor microenvironment regulation 17-19." (PMID 40083925, 2025).
tumor (continued). "For instance, FBXW7 functions as a tumor suppressor, and its inactivation can promote tumorigenesis and resistance to certain chemotherapies." (PMID 41184269, 2025). "FBXW7 was the most recurrently observed F-box protein among K562 hits, paired with many cell cycle related proteins (e.g. CDK2AP1, CDK4, CDKN1A, CKS1B), consistent with the known role of FBXW7 as a tumor suppressor." (PMID 39919746, 2025). "FBXW7 is a tumor suppressor that targets several oncoproteins, including MYC and cyclin E, for degradation." (PMID 40072110, 2025). "Previous studies have shown that SOX9 can be ubiquitinated by the E3 ligases KEAP1 or FBXW7, leading to its proteasomal degradation and consequent suppression of tumor progression." (PMID 41428171, 2025). "These regulators modulate FBXW7 expression and activity, influencing its role in key cellular processes such as cell cycle control, apoptosis, and tumor suppression." (PMID 40534867, 2025). "FBXW7 belongs to the F-box protein family and acts as a tumor suppressor against cancer progression." (PMID 39915362, 2025). "This microRNA, taken up by PCa cells, exerts pro-tumor effects by targeting and suppressing the tumor suppressor FBXW7." (PMID 41154598, 2025). "miR-92b-3p downregulates FBXW7 in CRC, and blocking it or overexpressing FBXW7 limits tumor growth and spread." (PMID 41373479, 2025). "This sponging effect decreases the expression levels of FBXW7 protein, which acts as a tumor suppressor, as a result of miR-197-3p overexpression and promotes carcinogenesis, tumor progression, especially in triple-negative BC." (PMID 41009512, 2025). "circ-FBXW7: This CircRNA acts as a sponge for miR-197, thus enhancing the expression of FBXW7, a tumor suppressor that plays a vital role in regulating cell proliferation and survival by down-regulating miR-197." (PMID 40896358, 2025). "In cancer, FBXW7 plays a critical role in modulating the tumor immune microenvironment by inhibiting macrophage M2 polarization through the targeted degradation of c-MYC." (PMID 40534867, 2025). "This regulatory mechanism highlights the potential of FBXW7 as a key modulator of cancer progression through its influence on the tumor immune microenvironment." (PMID 40534867, 2025). "In B‐cell lymphomas, decreased H3K27 acetylation suppresses FBXW7 expression, activates the NOTCH signaling pathway and downstream CCL2/CSF1, and promotes tumor cell proliferation and M2 polarization of tumor‐associated macrophages (TAMs)." (PMID 40761481, 2025). "FBXW7 acts as a tumor suppressor by degrading multiple oncogenic proteins, helping control proliferation, differentiation, and genomic stability." (PMID 41373479, 2025). "The number and size of tumor spheres were significantly reduced in HCC1937 cells after FBXW7 overexpression and increased greatly in MDA-MB-231 cells after FBXW7 silencing." (PMID 38268032, 2024). "For example, FBXW7, an E3 ligase for the crucial oncogene c‐Myc, can function as a tumor suppressor by targeting mTOR, HIF‐1α, c‐Myc, and SREBP1 for degradation." (PMID 39329019, 2024). "In most malignancies, FBXW7 depends on ubiquitin-mediated degradation of various oncoproteins to exert its tumor-suppressing function." (PMID 38268032, 2024). "In ESCC, low FBXW7 expression is related to high aggressiveness, while FBXW7 overexpression significantly inhibits tumor growth and invasion." (PMID 39749199, 2024). "Collectively, these data provide evidence that FBXW7 serves as a tumor suppressor in modulating the oncogenic phenotypes of TNBC cells." (PMID 38268032, 2024). "After that, a group of primary tumor cells acquired six additional mutations (in genes AKT1, BCL9L, B2M, FBXW7, MUTYH, RSPO2)." (PMID 38685065, 2024). "Concurrently, Pin1 negatively regulates FBXW7-mediated substrate degradation, contributing to tumor development." (PMID 39749199, 2024). "In this study, we applied IHC staining to a tissue microarray and revealed that FBXW7 has markedly lower expression in tumor samples." (PMID 38268032, 2024).